BCL2L1 (BCL2 like 1)
Diseases named in the same sentence as BCL2L1 in open-access papers (continued):
Sharing a sentence is not in itself a finding about the gene and the disease.
prostate carcinoma (126 papers, 2006 to 2026). A carcinoma that arises from epithelial cells of the prostate gland. "Provided preclinical data indicates that Adipose-derived stromal cells (A.S.C.)prevent prostate cancer cell growth, causing prostate cancer cell apoptosis with reduced activity of BCL2L1 by miR-145, so it can be a new and favorable therapeutic strategy in patients with prostate cancer." (PMID 36463254, 2022). "The anti-apoptotic proteins, specifically BCL2, BCL2L1 (Bcl-xL), and MCL1, are often overexpressed in cancer and are associated with resistance and disease progression in prostate cancer." (PMID 40704654, 2025). "In turn, KEAP1 induced mitochondrial phosphoglycerate mutase 5 (PGAM5) expression, a protein serine/threonine phosphatase that degrades Bcl-xL (BCL2L1) present in the mitochondrial membrane, inducing apoptosis of prostate cancer cells." (PMID 37296999, 2023). "BCL2L1 expression after radiotherapy has previously been investigated in prostate cancer patients undergoing external beam radiotherapy and found to be upregulated with increasing fatigue." (PMID 28443095, 2017). "This compound triggers apoptosis in human prostate cancer LNCaP and PC-3 cell lines by downregulation of BCL2 and BCL2L1." (PMID 36497321, 2022). "For example, miR‐1266‐5p is down‐regulated in prostate cancer, which regulates the apoptotic pathway by targeting the antiapoptotic genes BCL2 and BCL2L1." (PMID 32961635, 2020). "In LNCaP prostate cancer cells, reduced expression of SAM68 altered the expression of an important subset of genes involved in proliferation and apoptosis, including Bcl2L1, Clusterin, cdk2, cdk3, p16INK4, cyclin D1, Par-4, EGF and IGF-1." (PMID 25944080, 2015).
colon carcinoma (124 papers, 1998 to 2025). "Treatment of HCT116 colon cancer cells with 70 μg/ml of C. orbiculata extract resulted in an increase in the co-precipitation of hnRNPA2B1 with BCL2L1, BCL2, MDM2, cMYC, CD44, CDK6, and cJUN mRNA." (PMID 33163396, 2020). "The effects of C. orbiculata was similar to those of pladienolide B in that, just like C. orbiculata, pladienolide B switches splicing of hnRNPA2B1 and BCL2L1 to induce apoptosis in HCT116 colon cancer cells." (PMID 33163396, 2020). "We evaluated the association of hnRNPA2B1 with BCL2L1, BCL2, MDM2, cMYC, CD44, CDK6, cJUN, and TXNP in HCT116 colon cancer cells treated with 70 μg/ml of the crude extract." (PMID 33163396, 2020). "The analysis of gene expression considered five genes associated with apoptosis—BCL2 (B-cell CLL/lymphoma 2), BCL2L1 (BCL2 Like 1), BCL2L2 (BCL2 Like 2), CASP3 (caspase 3), and CASP9 (caspase 9), and was carried out in human colon cancer cells exposed to the IC50 dose of BVR." (PMID 38732003, 2024). "Indeed, several research groups have reported the importance of Chr20 amplification in colon cancer, and attributed such effect to the location of multiple oncogenes such as BCL2L1, AURKA, TPX2, and SRC on this chromosome." (PMID 38593144, 2024). "RT-PCR revealed that knockdown of hnRNPB1 can increase Bcl-xs in colon cancer cells resulting in an increase in caspase-3 cleavage and a decrease in cell viability, suggesting that hnRNPB1 modulates splicing of BCL2L1 and is functionally involved in cell proliferation in HCT116 colon cancer cells." (PMID 33163396, 2020). "Targeting hnRNPA2B1 splicing in colon cancer regulates splicing of BCL2L1 to induce apoptosis." (PMID 33163396, 2020). "qPCR showed that LPS increased CXCL1, ELK1, ICAM1 and ZFAND5 mRNA levels, but decreased BCL2L1 and E2F1 mRNA levels in the colon cancer cells." (PMID 37705049, 2023). "LPS also increased COX2, CXCL1, ELK1, ICAM1, TNFSF10 and ZFAND5 but decreased BCL2L1, CYP19A1 and E2F1 mRNA levels in the colon cancer cells." (PMID 37705049, 2023). "While it has initiated DNA fragmentation via activation of BAX and inhibition of BCL2 and BCL-XL (encoded by the BCL2L1 gene) in laryngeal carcinoma Hep-2 cells and colon carcinoma HL-60 cells, a decrease in BCL2 without alteration in BAX was reported in another study using U937 leukemic cells." (PMID 31873082, 2019).
ovarian carcinoma (124 papers, 2010 to 2026). A malignant neoplasm originating from the surface ovarian epithelium. "Associations between clinicopathological parameters and BCL2L1 expression in ovarian cancer tissue microarray (SE =)." (PMID 34351305, 2021). "Several studies report the expression of BCL2L1 in 60–70% of ovarian cancer and that BCL2L1 expression is associated with chemoresistant and recurrent disease." (PMID 22355333, 2012). "However, in another CRISPR‐Cas9‐based genetic screening study in the Kuramochi and OVSAHO ovarian cancer cell lines the anti‐apoptotic genes BCL2L1 (BCL‐XL) and BCL2L2 (BCL‐W) were found to be associated with chemotherapy resistance." (PMID 40242936, 2025). "Moreover, interaction analysis proved that two hub genes, SPTBN2 and BCL2L1, were highly associated with poor prognosis in ovarian cancer." (PMID 34179092, 2021). "Previous studies indicated BCL2 to be related to paclitaxel resistance in ovarian cancer, and up-regulation of BCL2L1 has been implicated in platinum and PARP inhibitor resistance in ovarian cancer." (PMID 38316463, 2024). "BCL2L1 located on 20q11.21 was recurrently gained in ~60% of ovarian cancer cases, ranking among the top 10 of all TCGA cases." (PMID 34351305, 2021). "BCL2L1 was differentially expressed between healthy and cancerous ovarian cases, showing substantially higher expression in ovarian cancer." (PMID 34351305, 2021). "In the resistance profile BCL2L1 coding for the protein BCL-XL is a predictor of cisplatin resistance in ovarian cancer." (PMID 29566065, 2018). "High levels of BCL-XL (B-cell lymphoma-extra large, also known as BCL2L1 or BCL2-like-1) are found in platinum resistant ovarian cancer cells and inhibition of BCL-XL confers sensitivity to chemotherapeutic agents." (PMID 26840082, 2016). "For example, BCL2L1, as a key protein in regulating programmed cell death or apoptosis, was found to be dysregulated in ovarian cancer cell lines and specimens that promoted cancer progression." (PMID 26099452, 2015). "A significant correlation was also reported between the nuclear mtTFA expression and the BCL2L1 expression in seven ovarian cancer cell lines as well as specimens of clinical ovarian cancer." (PMID 26307971, 2015). "However, it remains to be determined how BCL2L1 expression is regulated in response to cisplatin in ovarian cancer." (PMID 36733702, 2023). "Moreover, by using feature importance and comparing predicted ovarian cancer patient samples, BCL2L1 was identified as an important gene contributing to cisplatin resistance." (PMID 36733702, 2023). "Taking together, this suggest that modulating the expression of BCL2L1 (Bcl-xL) by epigenetic means might be a way to overcome cisplatin resistance in ovarian cancer cells." (PMID 22216282, 2011). "Lower expression of BCL2L1 and PLK2 displayed favorable outcomes independently, and when combined indicating a role of BCL2L1 and PLK2 in ovarian cancer." (PMID 36733702, 2023). "Morphology and ultra-structural changes and even a high amount of the anti-apoptotic proteins BCL2L1/Bcl-xL and BCL2 indicate that resveratrol stimulates cell death in ovarian cancer A2780 and CaOV3 cells via a different mechanism, compared to apoptosis." (PMID 36497321, 2022). "In paclitaxel-resistant ovarian cancer cells, blocking of STAT3 activity suppresses STAT3 downstream antiapoptotic regulatory genes BCL2L1, MCL1, and BIRC5, which increases paclitaxel sensitivity in paclitaxel-resistant ovarian cancer cells in vitro." (PMID 31861720, 2019).
pancreatic cancer (110 papers, 2003 to 2025). "PMAIP1 upregulation together with downregulation of the anti-apoptotic BCL2L1 protein have been correlated with increased apoptosis in pancreatic tumor cells treated with an oleanolic acid derivative." (PMID 27589063, 2016). "Similarly, the antiapoptotic BCL2L1 gene, which was found downregulated in sporaminin-induced apoptotic pancreatic cancer cells, is overexpressed in pancreatic adenocarcinoma." (PMID 34422220, 2021). "We observed significant overexpression of BCL2L1 in pancreatic tumor tissues." (PMID 33578795, 2021). "We found that miR-181c overexpression in pancreatic cancer cells significantly increased, but silencing of miR-181c reduced TEAD-dependent luciferase activity, and expression levels of the Hippo downstream genes CTGF, BIRC5 and BCL2L1 in pancreatic cancer cells." (PMID 26561204, 2015).
colorectal cancer (109 papers, 2003 to 2026). A primary or metastatic malignant neoplasm that affects the colon or rectum. "Here, we analyzed BCL2L1 expression and mutations in data from colorectal cancer patients in TCGA and GEO databases." (PMID 34141464, 2021). "TYMS and BCL2L1 were associated with the prognosis of colorectal cancer patients, which was consistent with previous reports of TYMS and BCL2L1 in other cancers." (PMID 34141464, 2021). "BCL2L1 was significantly associated with the prognosis of colorectal cancer patients, and high expression of BCL2L1 was markedly associated with lower survival rate in colorectal cancer patients." (PMID 34141464, 2021). "BCL2L1 plays a role in promoting survival in several solid tumor types and has been recently implicated as an amplified driver oncogene in colorectal cancer and gastric cancer." (PMID 27153554, 2016). "Using the online database, we also found that HDAC6 was positively correlated with the downstream target genes of STAT1 or NF-κB p65, such as MYC, RELA (p65) and BCL2L1, in colorectal cancer specimens." (PMID 38231305, 2024). "BCL2L1 silencing resulted in marked increases in apoptosis when combined with AZ’1569 in all KRASG12CMT colorectal cancer models, compared with the effects of each treatment alone." (PMID 36279564, 2023). "Using RNA-seq, IPA, and a siRNA screening approach, we identified that BCL2L1 was a critical mediator of resistance to cell death following KRASG12C inhibition in colorectal cancer cells." (PMID 36279564, 2023). "BCL2L1 has been reported as a key regulator in multiple cancer types including cervical cancer and colorectal cancer." (PMID 34141464, 2021). "We collected clinical samples to verify the expressions of TYMS and BCL2L1 in colorectal cancer and results of TYMS was consistent with the result of TCGA and GEO analysis." (PMID 34141464, 2021). "High expression of let-7c leads to the activation of Bax through regulating BCL2L1, thereby increasing the release of cytochrome c and promoting the apoptosis of colorectal cancer." (PMID 34141464, 2021). "The expression level of TYMS and BCL2L1 were significantly elevated in colorectal cancer patients than normal control." (PMID 34141464, 2021). "In TCGA and GEO, TYMS and BCL2L1 were significantly up-regulated and exhibited a moderately prognostic value for colorectal cancer.." (PMID 34141464, 2021). "We carried out the cBioPortal to determine the types and frequency of TYMS and BCL2L1 alterations in in colorectal cancer according to sequencing data from TCGA database." (PMID 34141464, 2021). "Using multi-dimensional analysis methods, we uncovered the potential function of BCL2L1 in colorectal cancer." (PMID 34141464, 2021). "The Cancer Genome Atlas (TCGA) and Gene Expression Omnibus (GEO) were analyzed to examine the expression and prognostic value of TYMS and BCL2L1 in colorectal cancer." (PMID 34141464, 2021). "The purpose of this study was to study the role of thymidylate synthetase (TYMS) and B-cell lymphoma-2 like 1 (BCL2L1) in the occurrence and development of colorectal cancer and its potential regulatory mechanism." (PMID 34141464, 2021).
colorectal cancer (continued). "There were 23 gastrointestinal diseases related to BCL2L1, among which the top 5 were stomach neoplasm, gastric carcinoma, esophageal carcinoma, gastric adenocarcinoma, colorectal carcinoma." (PMID 34141464, 2021). "By utilizing genomic data to identify tumors with BCL2L1 gain, we identified colorectal cancers as being potentially more dependent on BCL-XL and more susceptible to BCL-XL inhibition." (PMID 26134786, 2015). "We identified colorectal cancer as having the highest frequency of BCL2L1 amplification across all tumor types examined." (PMID 26134786, 2015). "In this study, we identified colorectal cancer as having a significant incidence of BCL2L1 amplification." (PMID 26134786, 2015). "miR-491-5p induces apoptosis in colorectal cancer cells by binding BCL2L1 (Bcl-XL) and inhibits cellular invasion of glioma cells." (PMID 24551047, 2014). "Expression of Bcl2-L1 was shown to be correlated to 20 q gain in colorectal cancer cell lines." (PMID 37736508, 2023). "Therefore, in vivo and in vitro experiments were necessary to uncover the pathogenesis of TYMS and BCL2L1 of colorectal cancer in the future study." (PMID 34141464, 2021). "Herein, TYMS and BCL2L1 were up-regulated in colorectal cancer patients in TCGA and GEO databases." (PMID 34141464, 2021). "TYMS and BCL2L1 were significantly connected with the prognosis of colorectal cancer patients." (PMID 34141464, 2021). "BCL2L1 was altered in 120 of 524 (22.9%) colorectal cancer patients." (PMID 34141464, 2021). "We also downloaded the immunohistochemistry pictures of BCL2L1 in colorectal cancer specimens." (PMID 34141464, 2021). "We also evaluated the prognostic value of TYMS and BCL2L1 in colorectal cancer." (PMID 34141464, 2021). "Finally, we collected clinical samples to verify the expressions of TYMS and BCL2L1 in colorectal cancer." (PMID 34141464, 2021). "To test this hypothesis, we selected a panel of 25 colorectal cancer cell lines with known copy number of BCL2L1." (PMID 26134786, 2015). "Colorectal cancer cell lines with BCL2L1 copy number >3 were more sensitive to A-1155463." (PMID 26134786, 2015). "In colorectal cancer cells, positive associations have been identified between CX26 and the pro-apoptotic gene BCL2-associated X protein (BAX) and between CX26 and the anti-apoptotic gene BCL2-like 1 (BCL2L1)." (PMID 24387126, 2014). "Our research demonstrated that LINC02595 is an oncogene in colorectal cancer (CRC) and established the presence of a LINC02595‐miR‐203b‐BCL2L1 axis in CRC, which might provide a new diagnostic biomarker and therapeutic targets for the treatment of this disease." (PMID 32064615, 2020). "Additionally, BCL2L1 gain may represent stratification biomarker for colorectal cancer patients undergoing treatment with a BCL-XL inhibitor." (PMID 26134786, 2015). "In colorectal cancer, the expression of HDAC6 was significantly positively correlated with MYC, p65, and BCL2L1 (p < 0.01), while negatively correlated with infiltration levels of CD8+T cells." (PMID 38231305, 2024). "In colorectal cancer and other types of cancer, the intrinsic apoptosis pathway is often out of whack, which means that anti-apoptotic proteins like BCL2 and BCL2L1 are overexpressed." (PMID 38287097, 2024). "Nex, we studied TYMS and BCL2L1 expression levels in multiple colorectal cancer samples from TCGA, and the results showed that TYMS and BCL2L1 were markedly up-regulated in colorectal cancer patients than normal control." (PMID 34141464, 2021). "We surveyed the percentage of copy number alternations of BCL2, BCL2L1 and MCL1 among a majority of these tumor samples and found that colorectal cancer has the highest percentage of BCL2L1 gain/amplification among all cancer types." (PMID 26134786, 2015). "However, the expression of BCL2L1 in colorectal cancer patients showed no significant change compared with adjacent normal controls." (PMID 34141464, 2021).
colorectal cancer (continued). "In the current study, the mutation ratio of TYMS and BCL2L1 were small, and the development of colorectal cancer was not connected with TYMS and BCL2L1 genomic changes." (PMID 34141464, 2021).